CRP (C-reactive protein)
Diseases named in the same sentence as CRP in open-access papers (continued):
Sharing a sentence is not in itself a finding about the gene and the disease.
myocardial infarction (continued). "In rats with acute myocardial infarction (AMI), 1,6-bis(phosphocholine)-hexane reversed the effect of human CRP, resulting in the attenuation of the size of myocardium infarct and restrained cardiac dysfunction." (PMID 31151201, 2019). "We explored the relationship between high-sensitivity C-reactive protein (hs-CRP) and AKI in acute myocardial infarction (AMI)." (PMID 31842300, 2019). "High CRP values were associated with increased in-hospital and follow-up all-cause mortality, in-hospital and follow-up major adverse cardiac events (MACE), and recurrent myocardial infarction (MI)." (PMID 28128312, 2017). "The genetic impact of TGFB1, FGB, CRP, IFNG, and PTGS and/or their biallelic combinations on myocardial infarction was found and replicated in Russians." (PMID 26658659, 2015). "In a rat myocardial infarction model, chronic VNS attenuated HF progression, prolonged survival time and improved the expression of biomarkers such as C-reactive protein (CRP)." (PMID 25366939, 2014). "High concentrations of salivary CRP, myoglobin and MPO, for example appear after myocardial infarction." (PMID 24915044, 2014). "Inflammatory response following acute myocardial infarction (AMI) has been documented since the 1940s and 1950s, including increased erythrocyte sedimentation rate (ESR), the C-reactive protein analysis (CRP), and the determination of serum complement (C′)." (PMID 23819098, 2013). "Of the 2925 subjects with CRP measured in the MIRACL study, 127 (4%) died, 205 (7%) had recurrent myocardial infarction, and 215 (7%) had recurrent unstable angina with objective evidence of ischemia over the 16 weeks of the study." (PMID 23525424, 2013). "We evaluated leukocyte counts and levels of CRP, fibrinogen, MPO, and PAPP-A in patients with stable and unstable angina pectoris, acute myocardial infarction, and healthy controls." (PMID 21188207, 2010). "Leukocyte counts and concentrations of fibrinogen, CRP, MPO, and PAPP-A were significantly increased in patients with acute myocardial infarction." (PMID 21188207, 2010). "In the current study, we evaluated leukocyte counts and levels of CRP, fibrinogen, MPO, and PAPP-A in patients with stable (SAP) and unstable angina pectoris (UAP), acute myocardial infarction (AMI), and healthy controls (CON)." (PMID 21188207, 2010). "The purpose of this study was to evaluate the impact of platelet aggregation, PFA-100 closure times and peak C-reactive protein (CRP), respectively, on the occurrence of death, myocardial infarction and ischemic cerebral events after an AMI." (PMID 19583836, 2009). "Furthermore, inflammatory markers such as CRP, IL-6, and TNFa, are associated with increased risk of congestive heart failure in older people without prior myocardial infarction; while CRP is strongly and independently associated with the occurrence of new onset heart failure." (PMID 19503842, 2009). "Of note, a high hs-CRP level measured after the first AMI predicts myocardial dysfunction and heart failure and it is suggested that hs-CRP plays an important role in the development of heart failure after myocardial infarction." (PMID 40649166, 2025). "In patients with acute myocardial infarction, elevated Hcy levels correlate with increased total cholesterol, low-density lipoprotein cholesterol (LDL-C), CRP, and pro-inflammatory cytokines, including TNF-α and IL-6, while showing an inverse correlation with the anti-inflammatory cytokine IL-10." (PMID 39898976, 2025). "CRP and serum albumin are the commonly used parameters, and several studies have shown a strong link between these inflammatory markers and the severity of CAD among myocardial infarction (MI) patients." (PMID 40922854, 2025).
myocardial infarction (continued). "Our previous studies demonstrated that the Glasgow Prognostic Score (GPS), which utilizes serum albumin (ALB) and serum C-reactive protein (CRP) levels, is a straightforward and potent method for assessing the prognosis of patients experiencing acute myocardial infarction." (PMID 39987233, 2025). "The results of another study revealed that diabetic individuals with acute myocardial infarction (AMI) who underwent primary PCI and were treated with SGLT-Is had lower CRP levels on admission compared to those in the control group, with a statistically significant difference (P < 0.001)." (PMID 39253345, 2024). "Participants with higher hs-cTnI and NT-proBNP levels were significantly older and had significantly higher rates of DM, pre-existing cardiovascular diseases, and myocardial infarction; significantly higher levels of ERI, CRP, eGFR and adiponectin; and significantly lower levels of GNRI." (PMID 38769120, 2024). "Post the six-month follow-up, myocardial infarction was reported in four (3.85%) patients in total, out of which one (1.39%) was in the low hs-CRP group and three (9.38%) were in the high hs-CRP group, though this is not statistically significant (P=>0.085)." (PMID 37273333, 2023). "During an episode of acute myocardial infarction (AMI), inflammatory processes involving fibrinogen, neutrophils, CRP, and IL-6 play a significant role in ischemia-reperfusion injury following reperfusion, leading to left ventricular remodeling and potentially developing heart failure." (PMID 37859889, 2023). "This technique proved successful in lowering CRP levels in patients with myocardial infarction but showed nonspecific results in patients with COVID-1997." (PMID 39554800, 2023). "CRP apheresis was then used in a non-randomized clinical trial after acute myocardial infarction (CAMI-1 trial)." (PMID 37626775, 2023). "In acute myocardial infarction, valsartan decreases IL-6, TNF-alfa and CRP." (PMID 35163696, 2022). "Besides this, the death group had lower LVEF, systolic and diastolic blood pressure, but higher CRP, AST, creatinine, urea nitrogen, NT-proBNP levels, LVESD and incidence of previous myocardial infarction events than the survival group (P < 0.05)." (PMID 35865381, 2022). "The Southern European Atlantic diet (SEAD), a common diet in the Iberian Peninsula, enabled reduced concentrations of C-reactive protein (CRP), triglycerides, and insulin, which could help prevent myocardial infarction." (PMID 35276919, 2022). "In our study, hs-CRP levels were significantly higher in acute myocardial infarction patients that had presented the primary end-point but not during separate analysis according to the type of AMI." (PMID 34362217, 2021). "Based on this, we simulated the probability of clinical deterioration for given AI-based severity score values for patients with or without prior myocardial infarction, immunodeficiency and CRP tertiles (T1 < 45.1 mg/L; T2 = 45.1–114.4 mg/L; T3 > 114.4 mg/L)." (PMID 34842822, 2021). "Calculation of the positive and negative likelihood ratios of the CRP/troponin ratio>500 to yield a true diagnosis of myopericarditis in the study population including all myocardial infarction patients yielded 3.8 and 0.5, respectively." (PMID 33886564, 2021). "After a median follow-up of 2.3 years, methotrexate failed to decrease the incidence of the primary endpoint (myocardial infarction or non-fatal stroke or cardiovascular death) and did not reduce CRP, IL-6, or IL-1β plasma levels." (PMID 34198968, 2021). "In acute myocardial infarction patients with and without DM, hs-CRP predicts in-hospital outcome and two-year mortality." (PMID 34753497, 2021). "Based on CRP concentrations, 917 patients with stable coronary artery disease (CAD; those who suffered a previous acute coronary syndrome or myocardial infarction 6 to 12 months before) were divided in two groups, low (CRP < 2 mg/L) or persistent (CRP ≥ 2 mg/L) inflammation." (PMID 33803115, 2021).
myocardial infarction (continued). "In terms of heart disease, oral administration of 1.5 mg of colchicine for 5 days can reduce hypersensitive C-reactive protein (hs-CRP), IL-1, IL-6, IL-8, and Neutrophilic Alkaline Phosphatase 3 (NALP3) levels in patients' serum with acute myocardial infarction." (PMID 32256634, 2020). "Hs-CRP can be used as a predictor of CVD, ischemic stroke, and myocardial infarction." (PMID 33094574, 2020). "Consistently with this theory, a similar hs-TnI peak value, an estimate of myocardial infarct size, was observed in our study in DM and non-DM patients, although the median hs-CRP level was significantly higher in the former group." (PMID 33081810, 2020). "Moreover, aronia berry extract has been shown to reduce blood cardiovascular risk markers such as oxidized-low-density lipoproteins (LDL), C-reactive protein (CRP), IL-6, soluble-ICAM-1, soluble-VCAM-1, and MCP-1 in patients after myocardial infarction." (PMID 31452653, 2019). "In further models of nonischemic HF, censoring at incident myocardial infarction when preceding HF diagnosis, effect estimates remained consistent except for CRP which further declined." (PMID 31862877, 2019). "In fact, CRP and FBG consistently predict new coronary events in patients with unstable angina and myocardial infarction, and mitochondrial oxidative stress has also been evidenced to be an independent risk factor for restenosis after percutaneous coronary intervention (PCI)." (PMID 31590380, 2019). "Many studies have identified elevated serum CRP levels in response to cardiovascular events and that CRP levels may strongly and independently predict adverse cardiovascular events, including myocardial infarction (MI), ischemic stroke, and sudden cardiac death." (PMID 29951057, 2018). "In a randomized control trial in patients with acute myocardial infarction, a short duration of treatment with vitamin D has significant impact on weakening the rise of CRP and IL-6 (but not TNF-α)." (PMID 32153865, 2018). "In univariate analysis advanced age (age >75 years), ACS on presentation, history of myocardial infarction (MI), current smoking status, elevated BMI (>25 kg/m2), AHG in those patients with ACS, DM, CKD, CRP and NYHA ≥2 were significant determinants of elevated GDF-15 plasma levels." (PMID 27056183, 2016). "Thus, it is also possible that a reduction in myocardial infarct size and inflammation reaction by emergency PCI or thrombolysis is responsible for the reduction in CRP in this group." (PMID 26819499, 2015). "Nonetheless, an elevated hs-CRP was a strong and independent predictor of death, nonfatal myocardial infarction, and recurrent angina pectoris." (PMID 24204905, 2013). "Since then, a number of studies have confirmed the occurrence of CRP in myocardial infarction and other noninfectious inflammatory conditions." (PMID 23819098, 2013). "In acute coronary syndromes, C‐reactive protein (CRP) strongly relates to subsequent death, but surprisingly not to recurrent myocardial infarction." (PMID 23525424, 2013). "Three patients with the highest hs-CRP tertile in the CAS group had nonfatal myocardial infarction events (0.6%)." (PMID 24204905, 2013). "There was no inflammatory response or myocardial infarction (white blood cell count, CRP, CK) after cell therapy." (PMID 22534049, 2012). "In patients with acute myocardial infarction (AMI), PTX3 peaked in plasma sooner than CRP, 6–8 h from symptom onset and, when measured with established markers including CRP, NT-proBNP and troponin-T, emerged as the only independent predictor of three-month mortality." (PMID 23285251, 2012). "We also demonstrated that CRP is an independent predictor of development of left ventricular systolic dysfunction after an ACS, as well, after controlling for common confounders (including myocardial infarction diagnosis)." (PMID 19503842, 2009).
myocardial infarction (continued). "For the control group taken together the median CRP concentration at admittance was 6 mg/L (IQR 2–19 mg/L, range 1–303 mg/L), 5 mg/L (IQR 2–12 mg/L) for those with cerebral infarction and 7 mg/L (IQR 2–24 mg/L) for those with myocardial infarction." (PMID 18706087, 2008). "Such an effect is implicated by findings from rodent models of beneficial effects of post-myocardial infarction CRP lowering, but to our knowledge has not be demonstrated in humans." (PMID 18714384, 2008). "Therefore, the present study aimed to assess and compare the discriminatory levels of salivary MIP-1α, adiponectin, and C-Reactive protein in healthy individuals, stage III periodontitis patients, and post-myocardial infarction patients with stage III periodontitis." (PMID 38433948, 2024). "In this cluster, troponin, a strong independent predictor in myocardial infarction, was positively correlated only with neutrophil or neutrophil-associated inflammatory molecules (NLR, S100A8/A9, NETS and IL-6) but not with ESR, Ferritin, Fibrinogen, and CRP." (PMID 38791147, 2024). "Beyond the prognostic value of CRP in patients with an established diagnosis of HF, it might have the role of predicting HF development in patients without prior myocardial infarction." (PMID 38541167, 2024). "Upon testing for outcomes such as angina, myocardial infarction, resuscitated cardiac arrest, or CHD death from CHD, statistically significant predictors were found to be coronary artery calcium, family history, high-sensitivity C-reactive protein (CRP), and ankle-brachial index." (PMID 38756258, 2024). "However, results from the multi-center pilot CAMI-1 (CRP Apheresis in Acute Myocardial Infarction-1) study were inconclusive in regard with correlation of reduced CRP levels with myocardial infarct size because the study was not randomized." (PMID 37564640, 2023). "Initial tests showed elevated troponin T, glucose, CRP, and D-dimer levels, and electrocardiography and transthoracic echocardiography showed abnormalities suggesting acute myocardial infarction, but angiography did not reveal any significant coronary artery blockages." (PMID 37671142, 2023). "One study by our group identified advanced age, no smoking, previous myocardial infarction, Killip class, serum creatinine, C-reactive protein, time-to-treatment interval, LVEF, baseline TIMI flow and scintigraphic initial perfusion defect as correlates of CNR." (PMID 37685660, 2023). "Inhibition of IL-1β by canakinumab, reduced the rates of nonfatal myocardial infarction, nonfatal stroke, or cardiovascular death compared with placebo in patients with prior myocardial infarction and high sensitivity CRP ≥ 2 mg/L, with consistent effects regardless of DM." (PMID 37735399, 2023). "All these suggest that inflammation is involved in the process of AMI, but it is not clear whether CRP is related to complications after myocardial infarction." (PMID 35066901, 2022). "Interestingly, in spite of significant reduction of CRP plasma levels via CRP apheresis in both disease entities, we have not observed such effects in our patients suffering from acute myocardial infarction or COVID-19 disease." (PMID 35407379, 2022). "Patients with higher CRP levels (CRP > 3 mg/dL) were associated with a significantly increased rate of MACE which included all-cause death, recurrence of nonfatal myocardial infarction, and target vessel revascularization (TVR) in terms of long-term clinical outcome." (PMID 34900087, 2021). "In contrast to CRP, measurement of systemic levels of PTX3 seems to be a much faster (peak levels reached at 7.5 h versus 24 h after hospital admission, respectively) and more reliable (faster regression to normal values) marker for acute myocardial infarction." (PMID 32246830, 2020).
myocardial infarction (continued). "Many molecules like troponins, brain natriuretic protein (BNP), ST2/IL-33, C-reactive protein (CRP), TNF, IL-1β, and IL-18 cytokines have been already examined as molecular markers for diagnosing or predicting different cardiac disturbances like myocardial infarction, heart failure, or myocarditis." (PMID 33172097, 2020). "However, the exact mechanisms leading to an increase in IL-6 and CRP after myocardial infarction have not been sufficiently characterised." (PMID 32537679, 2020). "CRP supplementation may not accurately mimic the pathological increase in serum CRP in response to myocardial infarction, because pathologically increased CRP may interact with a variety of tissues and cells." (PMID 31063484, 2019). "Indeed, hs-CRP serum level is an inflammatory marker that increased within two days following ACS, but not in unstable angina; this increment continued for three months subsequent to myocardial infarction." (PMID 29337850, 2018). "The CMV genome copynumber was correlated with the plasma CRP level (p = 0.002).These findings indicate a potential relationship between CMV activation andatherosclerosis exacerbation that, in turn, leads to the development ofunstable angina and acute myocardial infarction." (PMID 27437144, 2016). "Interestingly, a study indicated that the leukocyte count was qualified to predict myocardial infarct size whereas CRP was not in patients with ST-segment elevated myocardial infarction who had been treated with primary percutaneous coronary intervention." (PMID 24599246, 2014). "Following myocardial infarction (MI), PTX3 plasma levels peak within 7.5 hours as compared to CRP which peaks around 50 hours." (PMID 23690668, 2013). "Complement activation by CRP was reported to contribute to ischemia-reperfusion injury in a rat model of myocardial infarction although the findings are difficult to interpret because in this model endogenous rat CRP played no role and infusion of human CRP was required to activate rat complement." (PMID 24167754, 2013). "The intervention group showed a significantly reduced incidence of repetitive atherothrombotic events (non-fatal myocardial infarction (MI), non-fatal stroke, or cardiovascular death) and a reduction in the C-reactive protein level." (PMID 40141106, 2025). "The outcomes were total cholesterol, LDL-C, high-density lipoprotein cholesterol (HDL-C), non-HDL cholesterol, triglyceride (TAG), apolipoprotein B (APOB), high-sensitivity CRP (hs-CRP), major cardiovascular events (MACE), cardiovascular mortality, and myocardial infarction (MI)." (PMID 40792240, 2025). "Furthermore, tocilizumab, a potent Il6 receptor antagonist, has demonstrated robust anti-inflammatory efficacy in patients with non-ST-segment elevation myocardial infarction, as evidenced by substantial reductions in high-sensitivity C-reactive protein (hs-CRP) and cardiac troponin T (cTnT) levels." (PMID 41347019, 2025). "However, how CRP is involved in myocardial infarction has not been fully elucidated." (PMID 31063484, 2019). "For example, elevated CRP, TNF-α, and IL-6 levels have been associated with both myocardial infarction (MI) and non-traumatic FF." (PMID 30630495, 2019). "The C-reactive protein-to-albumin ratio (CAR) serves as a composite marker reflecting both systemic inflammation and nutritional status and may enhance prognostic accuracy in myocardial infarction (MI)." (PMID 41018414, 2025). "MACE, microembolic signals and hs-CRP concentration in CAS group: No death, myocardial infarction, ischemic or hemorrhagic stroke, need of revascularization occurred during the 30-day post-procedural period." (PMID 31814936, 2019). "Significantly positive correlation of resistin was observed with TLC only in hypertensive patients of myocardial infarction (r = 0.459, n = 20, p = 0.042) while in other study groups correlation between resistin and TLC as well as CRP was non-significant." (PMID 31258568, 2019).